CD40LG (CD40 ligand)
Diseases named in the same sentence as CD40LG in open-access papers (continued):
Sharing a sentence is not in itself a finding about the gene and the disease.
diabetes (131 papers, 2004 to 2026). "In other studies, CD40 ligand + PMPs of CKD patients can be reduced by the vitamin D2 derivative, paricalcitol, or lipid-lowering treatment (LLT) with simvastatin in the settings of diabetes mellitus (DM)-CKD." (PMID 33202988, 2020). "Firstly, activated platelets could express soluble CD40 ligand (CD40L) and CD40L and its receptor CD40 extensively involved in oxidative stress and inflammatory pathways, which may play a role in the development of diabetes." (PMID 29651306, 2018). "Moreover, B and T cell responses are altered in people with diabetes in several ways for instance, reduced expression of co-stimulatory molecules (CD69, CD28, CD40 ligand) or interleukin-12 receptor on T cells which leads to lower production of interferon and granzyme B." (PMID 36105809, 2022).
hypogammaglobulinemia (122 papers, 2004 to 2026). "Bruton's agammaglobulinemia (~30% of cases), CD40 ligand deficiency (immune deficiency with IgM hypergammaglobulinemia, 50% of cases), variable hypogammaglobulinemia and unclassified hypogammaglobulinemia can be accompanied by neuropenia." (PMID 21595885, 2011).
multiple myeloma (120 papers, 2008 to 2026). "In multiple myeloma (MM), interaction with bone marrow stromal cells (BMSCs) via CD40–CD40 ligand (CD40LG) signaling increases iron accumulation and activates the steroid biosynthesis pathway in MM cells, leading to enhanced lanosterol production." (PMID 40659633, 2025).
pneumonia (117 papers, 2010 to 2026). An acute, acute and chronic, or chronic inflammation focally or diffusely affecting the lung parenchyma, caused by an infection in one or both of the lungs (by bacteria, viruses, fungi, or mycoplasma.). "Our data show that systemic immune cells like CD3+ T cells are activated to regulate various phases of the immune response through binding of increased CD154 (CD40‐ligand) to CD40 in acute pneumonia, as another indication in response to pathogens." (PMID 34841705, 2021).
Thrombocytopenia (105 papers, 2009 to 2026). A reduction in the number of circulating thrombocytes. "The initial attempts at blocking the CD40-CD154 (CD40 Ligand) costimulatory pathway were complicated by thrombocytopenia and thrombotic events, as CD154 is also expressed on platelets." (PMID 38993853, 2023). "While HIV-infected individuals often present with thrombocytopenia, they have also been reported to have increased platelet activation, as measured by an upregulation of expression of CD62P (P-selectin), CD40 ligand, glycoprotein IV, and RANTES." (PMID 33777022, 2021).
co-infection (100 papers, 2008 to 2026). "Notably, TGF-β signaling (TGFB1-TGFBR1-TGFBR2) was extinguished during HIV-mono infection yet reappeared in co-infection, whereas IL16-CD4 and CD40LG-(ITGAM/ITGB2) interactions disappeared with HIV-mono and did not recover, underscoring stage-specific rewiring of T-cell communication networks." (PMID 41394852, 2025).
melanoma (89 papers, 1974 to 2026). A malignant, usually aggressive tumor composed of atypical, neoplastic melanocytes. "Human melanoma cells were infected by OVs armed with costimulatory molecules CD40 ligand (CD40L) and 4-1BB ligand (4-1BBL)." (PMID 33738337, 2021). "Herein, we demonstrate immune profiling data from melanoma patients treated with an adenovirus-based CD40 ligand gene therapy (AdCD40L)." (PMID 28427434, 2017). "Primary human B cells activated in vitro with CD40 ligand and subsequently pulsed with melanoma tumor antigens, efficiently processed and presented MHC class II-restricted peptides to specific CD4+ T cell clones, generating melanoma-specific T cells." (PMID 28507802, 2017). "For example, the adenoviral vector, AdCD40L, expressing a CD40 ligand exhibited complete tumor regression in 5 of 19 canine melanoma patients after intratumoral injection." (PMID 24841386, 2014). "TriMix, a mixture of monocyte-derived dendritic cells electroporated with mRNA encoding CD70, CD40 ligand, and constitutively active TLR4, as well as the tumor-associated antigens tyrosinase, gp100, MAGE-A3, or MAGE-C2 were administered together with ipilimumab in patients with advanced melanoma." (PMID 36830845, 2023). "Consistent with these in vitro data, CD47 mRNA expression in TCGA melanomas had highly significant positive correlations with MCL1, CD40LG, TIGIT, and TNF mRNA expression." (PMID 36768931, 2023). "Based on their strong positive correlations with CD47 mRNA expression in the TCGA melanoma data, we selected MCL1, CD40LG, TNF, and TIGIT to examine their regulation by CD47 signaling in human Jurkat T lymphoblast cells." (PMID 36768931, 2023).
thrombosis (86 papers, 2005 to 2026). "Lower platelet numbers noted in ICs could be attributed to ongoing thrombosis, while raised levels of P-Selectin and CD40 ligand suggest functional platelet activation." (PMID 37384264, 2022).
Hypertension (85 papers, 2007 to 2026). The presence of chronic increased pressure in the systemic arterial system. "CD40 ligand (CD40L) signaling regulates ED via immune cell recruitment and platelet activation in mouse models of hypertension, the mechanism of which extended to mouse models of obesity, implicating CD40L as a therapeutic target for lipid dysmetabolism." (PMID 34277732, 2021).
Stroke (83 papers, 2010 to 2026). Sudden impairment of blood flow to a part of the brain due to occlusion or rupture of an artery to the brain. "In the context of stroke, several platelet‐related factors—such as von Willebrand factor, CD40 ligand, and monocyte–platelet aggregates—have been implicated in poor functional outcomes based on evidence from both basic animal studies and human serum analyses." (PMID 41550466, 2026). "In multivariate analyses, D-dimer was associated with reticulocyte count, lactate dehydrogenase, NT-proBNP and history of stroke; soluble CD40 ligand was associated with WBC count and platelet count; and MPTF procoagulant activity was associated with hemoglobin and history of acute chest syndrome." (PMID 22253781, 2012). "In patients in the SS/SD/Sβ0 thalassemia group, D-dimer was associated with a history of stroke (p = 0.049), TAT was associated with a history of retinopathy (p = 0.0176), and CD40 ligand was associated with the frequency of pain episodes (p = 0.039)." (PMID 22253781, 2012). "However, adhesion events were markedly increased following the introduction of arginine-glycine-aspartate (RGD)-labelled synthetic MPs or endogenously-derived EVs from experimental stroke animals carrying excess RGD proteins, including vitronectin, CD40-ligand and thrombospondin-1." (PMID 31676801, 2019). "Moreover, as there exist also white platelet-rich thrombi, platelet activation is another phenomenon that could provide with some good candidates, like CD40 ligand (CD40L), CD63 or P-selectin mainly associated with LAA strokes although these biomarkers have only been compared among non-CE strokes." (PMID 21804778, 2010).
breast carcinoma (79 papers, 1977 to 2026). "In breast cancer, CD40LG has been developed as a key prognostic gene associated with the tumor microenvironment." (PMID 37540295, 2023). "Likewise, high CD40LG expression was associated with better survival in all breast cancer (hazard ratios of 0.71–0.89, P = 3.9e-05) and triple negative breast cancer (hazard ratios of 0.32–0.78, P = 0.0018) data set." (PMID 32256143, 2020). "According to related research in breast cancer, the high expression of CD40LG indicates a higher survival rate." (PMID 40690457, 2025). "CD40LG plays a role in angiogenesis and has been described as a core prognostic indicator in breast cancer." (PMID 40438247, 2025). "Gene expression analysis from in vitro mammosphere formation revealed IFNG, CXCR5, CD40LG, TBX21, and IL2RG to be associated with the CSC phenotype and also displayed prognostic value for patients with breast cancer." (PMID 39001456, 2024). "Gene expression analysis revealed IFNG, CXCR5, CD40LG, TBX21 and IL2RG to be associated with the CSC phenotype and also displayed prognostic value for patients with breast cancer." (PMID 38831317, 2024). "CD40LG has been identified as a prognostic biomarker that regulates TME via immune processes in breast cancer." (PMID 35837383, 2022). "Soluble recombinant CD40 ligand (CD40L) molecules effectively inhibited the growth of breast cancer in vivo by inducing apoptosis of breast cancer cells." (PMID 33907159, 2021). "CD40LG inhibited the in vitro growth of CD40+ human breast cancer lines by blocking the cell cycle and inducing apoptosis of breast cancer cells." (PMID 33907159, 2021). "Here, we analyzed both CD40/CD40 ligand expression in breast cancer cells and tissues using public data sets and overall survival analysis in ungrouped breast cancer patients, as well as in the triple-negative breast cancer subtype." (PMID 32256143, 2020). "Further analysis of the genetic structure and functionality of CD40 and CD40LG would allow the development of more useful prognostic factors and prognostic prediction tools in breast cancer subtypes." (PMID 32256143, 2020). "Serum concentrations of epidermal growth factor, soluble CD40-ligand and proapolipoprotein A1 were increased in breast cancer patients." (PMID 19400944, 2009). "CD40LG reduced the apoptosis of breast cancer cells induced by chemotherapeutic drugs." (PMID 33907159, 2021). "Data analysis of these breast cancer cell lines revealed extremely low CD40LG expression as well." (PMID 32256143, 2020). "Similarly, the treatment of human breast cancer cells with a recombinant CD40 ligand (CD40L) inhibited cell growth in vitro and in vivo." (PMID 18086299, 2007). "Apart from CD40 expression, membrane CD40LG expression has been rarely detected in tumor-infiltrating lymphocytes in breast cancer tissues, supporting their low capacity to inhibit growth of breast cancer cells via the CD40–CD40LG axis." (PMID 32256143, 2020). "Four known biomarkers (CHEK2 in both plasma and urine, CDKN1B, PCNA, and THBS1) were identified as false positives (red) in our breast cancer list, and seven (KRAS, GDNF in both breastmilk and plasma, MYCL1 in both blood and serum, CD40LG, CGA, CTAG1A, ERCC6, and HRAS) in our lung cancer list." (PMID 25379168, 2014). "Treatment with CD40 ligand decreased proliferation of BT-20 and T-47D cells which are CD40-positive, but did not change the growth of CD40-negative breast cancer cell lines, as detected in MCF-7 or ZR-75-1 cells, supporting the idea that CD40–CD40LG axis modulates proliferation of cancer cells." (PMID 32256143, 2020).
Arthritis (78 papers, 2005 to 2026). Inflammation of a joint. "In this report, we present a patient with CD40 ligand (CD40L) deficiency who had arthritis and hypertransaminasemia with no history of serious infection until 8 years of age." (PMID 25541662, 2014). "The transcription factor STAT-1 (signal transducer and activator of transcription-1) plays a pivotal role in the expression of inflammatory gene products involved in the pathogenesis of arthritis such as various cytokines and the CD40/CD40 ligand (CD40/CD40L) receptor-ligand dyad." (PMID 16507120, 2006).
B-cell lymphoma (78 papers, 1998 to 2025). "Top proteins specifically associated with germinal center-derived B-cell lymphoma risk included LSAMP, FDCSP, SERPINA9, CCL21 and CD40LG." (PMID 40894013, 2025).
anemia (72 papers, 2008 to 2026). A reduction in the number of red blood cells, the amount of hemoglobin, and/or the volume of packed red blood cells. "Even so, a number of marginal susceptibility genotype associations were also observed between specific gene mutations and anaemia (GBP7), CM (CD40LG), hyperparasitaemia (NOS2), hyperpyrexia (CD36, CD40LG, G6PD), SMA (EMR1) and UM (NOS2, EMR1)." (PMID 24934404, 2014).
leprosy (70 papers, 2005 to 2026). Leprosy is a chronic infectious disease affecting primarily the skin and peripheral nervous system. "Indoleamine 2,3-dioxygenase 1 (IDO1) expression alone was highly discriminatory, followed by TLR10, BLK, CD38, and SLAMF7, whereas the HS3ST2 and CD40LG mRNA separated multi- and paucibacillary leprosy." (PMID 34695167, 2021). "The HS3ST2 gene was consistently more expressed in MB leprosy lesions compared to PB, whereas the opposite was observed for CD40LG and CCR6." (PMID 34695167, 2021). "After mechanistic validation of our findings, quantifying expression levels of HS3ST2 and CD40LG from leprosy lesions could be useful to assess immune responsiveness against M. leprae, help patient stratification and/or provide a basis for host-based adjuvant treatment for leprosy lesions." (PMID 34695167, 2021).
Obesity (69 papers, 2011 to 2025). Accumulation of substantial excess body fat. "Obesity is associated with increases in platelet activation and the parameters that reflect platelet activation, such as the mean platelet volume, soluble P-selectin, and soluble CD40 ligand (sCD40L), are also increased in the blood of obese patients." (PMID 26824242, 2016). "In another study, obesity was associated with a decreased number of activated CD8+ T cells expressing CD28, CD40 ligand (CD40L), IFNγ as well as both IFNγ and GrB, and both CD28 and interleukin 12 receptor (IL12R)." (PMID 36295052, 2022). "Soluble CD40 ligand (sCD40L) was found to be lower in individuals with obesity." (PMID 40153192, 2025). "In conclusion, our research found that CD40LG and GZMB played important roles in immunity and inflammation modules in the VAT of OSA patients, and pro-inflammatory M1 macrophage in VAT was a hallmark feature in OSA patients independently of obesity." (PMID 36923793, 2023). "Interestingly, CD40 ligand (CD40L) in humans has been correlated with obesity." (PMID 26005433, 2015). "It is generally believed that the cluster of differentiation 40 (CD40)/CD40 ligand (CD40L) pathway is an integral part of the onset and maintenance of inflammatory reactions in obesity." (PMID 36505468, 2022).
lymphopenia (68 papers, 2009 to 2025). Reduction in the number of lymphocytes. "Thus, CD4+ T lymphopenia, CD40 ligand absence, or interfered IFN-γ pathway could hamper macrophages to eliminate intracellular TM." (PMID 36180657, 2022).
tuberculosis (60 papers, 2011 to 2026). A chronic, recurrent infection caused by the bacterium Mycobacterium tuberculosis. "CD40 ligand (CD40L) deficiency predisposes humans to opportunistic infections by intracellular bacteria and can be correlated with severe tuberculosis in macaques." (PMID 31266499, 2019).
X-linked hyper-IgM syndrome (55 papers, 2007 to 2025). "Of the 30 patients with AIN, one patient with X-linked hyper-IgM syndrome or CD40 ligand (CD40L) deficiency presented with pre-transplant AIN that persisted after transplantation." (PMID 40777012, 2025). "X-linked Hyper IgM Syndrome is caused by mutations in the CD40LG gene, disrupting normal immunoglobulin class switching." (PMID 39712011, 2024). "One case of X-Linked Hyper IgM Syndrome, attributed to an in-frame deletion (p.Tyr146del) in the CD40LG gene, was reported." (PMID 37592284, 2023). "A case was presented, and the characteristics of four cases of CD40LG-associated X-linked hyper-IgM syndrome with pulmonary alveolar proteinosis were summarized." (PMID 37173671, 2023). "In experiments involving B cells from patients with X-linked hyper-IgM syndrome, the combination of soluble CD40 ligand (sCD40L) with IL-4 or IL-10 prompted B cell proliferation and spurred their differentiation toward the secretion of IgG, IgA, and IgE." (PMID 37892436, 2023). "X-linked hyper-IgM syndrome (XHIM) is caused by mutations in the CD40LG gene encoding CD40 ligand (CD40L)." (PMID 36091069, 2022). "CD40 ligand deficiency (also known as X-linked hyper-IgM syndrome) is an IEI that results from mutations in the CD40LG gene." (PMID 35783679, 2022). "A retrospective review of all the CD40LG mutant-induced X-linked hyper IgM syndromes (XHIGM, OMIM #308230) had been conducted according to their medical archives." (PMID 35804376, 2022). "CD40 ligand (CD40L) deficiency or X-linked Hyper IgM syndrome (HIGM) is a primary immunodeficiency that increases susceptibility to several opportunistic infections." (PMID 34335625, 2021). "Eventually a pathogenic nonsense variant in the CD40 ligand gene [p.(Arg11∗)] was identified by whole genome sequencing, thus enabling the diagnosis of X-linked hyper IgM syndrome." (PMID 33013931, 2020). "X-linked hyper-IgM syndrome is a type of primary combined immunodeficiency disorder caused by mutations in CD40 ligand." (PMID 32541472, 2020). "X-linked hyper-IgM syndrome (XHIM) is caused by mutations in the CD40 ligand (CD40L) gene." (PMID 32935622, 2021). "An example of this can be found in one of the original descriptions of mutations in CD40LG, which reported detectable expression of CD40L on activated CD4+ T cells from one patient with X-linked hyper-IgM syndrome despite the presence of a predicted inactivating mutation." (PMID 31552044, 2019). "X-Linked Hyper-IgM Syndrome is caused by mutations in the CD40LG (aka TNFSF5) gene at Xq26.3." (PMID 26029204, 2015). "Thus, ineffectual Fas-FasL interactions might produce a T cell activation defect in a fashion similar to that seen with mutations in CD40-ligand (CD154) in X-linked hyper-IgM syndrome." (PMID 17605793, 2007). "Further evaluation for X-linked hyper IgM syndrome revealed normal expression of the CD40 marker, CD40 ligand, and replication function." (PMID 41044616, 2025). "The vast majority of HIGM patients are male and affected by X-linked hyper-IgM syndrome (HIGM1), caused by mutations affecting T cell expression of the CD40 ligand CD40LG." (PMID 34198536, 2021). "Mutations in the CD40 ligand (CD40L) gene (CD40LG) lead to X-linked hyper-IgM syndrome (X-HIGM), which is a primary immunodeficiency (PID) characterized by decreased serum levels of IgG and IgA and normal or elevated IgM levels." (PMID 29780795, 2018). "X-linked hyper-IgM syndrome (XHIGM) is one type of primary immunodeficiency diseases, resulting from defects in the CD40 ligand/CD40 signaling pathways." (PMID 25215306, 2014). "Genetic mutations in the CD40LG gene lead to X-linked hyper IgM syndrome (XHIM), a condition marked by the absence of T cell-dependent humoral immunity and specific IgG antibodies." (PMID 40129981, 2025).
X-linked hyper-IgM syndrome (continued). "CD40 ligand (CD40L) deficiency is a combined immunodeficiency (CID), characterized by a defective T–B lymphocyte cross talk and class-switch recombination (CSR), also called X-linked hyper-IgM syndrome (XHIGM)." (PMID 35572607, 2022).
chronic lymphocytic leukemia (53 papers, 1982 to 2026). "The co-stimulatory molecule CD40 ligand expressed from a recombinant adenoviral vector in autologous chronic lymphocytic leukemia cells has been tested in a recent clinical trial with encouraging results." (PMID 15485577, 2004). "Primary chronic lymphocytic leukemia (CLL) cells from patients can be cultured in vitro and induced to proliferate when stimulated with CD40 ligand (CD40L), which induces both the classical and alternative NF-κB pathways." (PMID 25255445, 2014).
myocardial infarction (50 papers, 2010 to 2025). Gross necrosis of the myocardium, as a result of interruption of the blood supply to the area, as in coronary thrombosis. "Furthermore, the plasma SCUBE1 level was shown to be positively correlated with soluble CD40 ligand (sCD40L) level in hemodialysis patients, signaling myocardial infarction." (PMID 37237303, 2023).
lupus nephritis (49 papers, 2013 to 2025). Glomerulonephritis in the context of systemic lupus erythematosus. "Similarly, remission of proliferative lupus nephritis after B-cell depletion was preceded by the reduced expression of CD40 ligand on T cells, indicating a disruption of the critical CD40–CD40L axis that facilitates T-/B-cell crosstalk." (PMID 41515926, 2025).